H2AX (H2A.X variant histone)
Diseases named in the same sentence as H2AX in open-access papers (continued):
Sharing a sentence is not in itself a finding about the gene and the disease.
adenoma (1 paper, 2023). A neoplasm arising from the epithelium.
allergic asthma (1 paper, 2020). A asthma with a basis in a pathological type I hypersensitivity reaction. "Furthermore, in a house dust mite (HDM) mouse model of allergic asthma, p-H2AX is increased in the airway epithelium." (PMID 32117962, 2020).
anaemia (1 paper, 2016). "Taken together, these results demonstrate that the loss of H2AX in mice mimics the anaemia, dyserythropoiesis, and increased Howell-Jolly bodies observed in MDS patients." (PMID 26791933, 2016). "H2AX knockout mice showed cell-autonomous anaemia and erythroid dysplasia, mimicking dyserythropoiesis in MDS." (PMID 26791933, 2016). "Complete blood count showed that H2AX knockout mice exhibited macrocytic anaemia (i.e., increased mean corpuscular volume) but other blood lineages, including white blood cells and platelets, were unaffected, consistent with high H2AX expression in the erythroid lineage." (PMID 26791933, 2016).
asthma (1 paper, 2020). "In patients with asthma, the airway epithelium possesses an increased level of p-H2AX, suggesting that DNA damage is greater, or that DNA repair mechanisms are impaired in asthmatic airways." (PMID 32117962, 2020).
Ataxia (1 paper, 2021). Ataxia refers to impaired coordination of voluntary muscle movement.
benign prostatic hyperplasia (1 paper, 2012). A non-cancerous nodular enlargement of the prostate gland. "γ-H2AX foci/cell in human leukapheresis-derived mononuclear cells, stratified by disease subgroups which contribute to oxidative stress and/or DNA damage (with the exception of benign prostatic hyperplasia)." (PMID 23029205, 2012).
Bloom syndrome (1 paper, 2016). Bloom syndrome (BSyn) is a rare chromosomal breakage syndrome characterized by a marked genetic instability associated with pre- and postnatal growth retardation, facial sun-sensitive telangiectatic erythema, increased susceptibility to infections, and predisposition to cancer. "Despite lower initial H2AX phosphorylation and severely delayed dephosphorylation compared to wildtype cells, blm‐P868L cells responded significantly better to repeated CPT exposure than Bloom syndrome cells." (PMID 26788541, 2016).
breast disease (1 paper, 2023). "Even though in our analysis we found H2AX to be down-regulated in M/N group, it is important to note that we detected H2AX in saliva and this could be conveniently used for monitoring breast disease." (PMID 36835577, 2023).
cataract (1 paper, 2012). Partial or complete opacity of the crystalline lens of one or both eyes that decreases visual acuity and eventually results in blindness. "In addition, there were trends toward increased γ-H2AX foci in patients with cataracts (34% increase, p<0.10) and in sleep apnea patients (44%, p<0.10)." (PMID 23029205, 2012). "We found a trend of increased γ-H2AX foci (34%, p = 0.099) in patients with cataracts." (PMID 23029205, 2012). "Participants with cataracts had an increase in γ-H2AX foci/cell compared to those without cataracts (5.51±1.30 compared to 4.11±0.28), but the difference was not significant (p = 0.099)." (PMID 23029205, 2012).
Cdt (1 paper, 2020). "There is little direct evidence of DNA damage in Cdt treated mammalian cells; however, investigators have observed that some types of Cdt treated cells exhibit activation of the DNA damage response (DDR); this responses utilizes phosphorylation of H2AX as a surrogate for DNA damage." (PMID 32655562, 2020).
chondrosarcoma (1 paper, 2019). A malignant cartilaginous matrix-producing mesenchymal neoplasm arising from the bone and soft tissue. "Chondrosarcoma patient samples showed an increase in γ-H2AX foci after 5 Gy radiation treatment." (PMID 31160965, 2019). "In addition, radiosensitivity of chondrosarcoma patient samples was determined by counting γ-H2AX foci after ex vivo radiation." (PMID 31160965, 2019). "Chondrosarcoma tumor explants were irradiated after which γ-H2AX foci were counted." (PMID 31160965, 2019). "Therefore, the aim of our study was to examine whether sensitivity to γ-radiation can be observed in central conventional chondrosarcoma cell lines by determining clonogenic survival and γ-H2AX foci induction after radiation." (PMID 31160965, 2019). "Irradiated chondrosarcoma patient tissue presented a variable increase in γ-H2AX foci compared to non-radiated tissue." (PMID 31160965, 2019).
chronic kidney disease (1 paper, 2024). Impairment of the renal function secondary to chronic kidney damage persisting for three or more months. "Additionally, skeletal muscle atrophy associated with chronic kidney disease (CKD) and spinal muscular atrophy (SMA) is linked to heightened γ-H2AX expression." (PMID 39125931, 2024).
clear cell carcinomas (1 paper, 2020). "As expected, we demonstrate abundant expression of H2AX in high-grade serous OC, mucinous adenocarcinomas, and clear cell carcinomas." (PMID 32887437, 2020).
cleft palate (1 paper, 2021). Cleft palate is a fissure type embryopathy that affects the soft and hard palate to varying degrees. "To understand the etiology of cleft palate induced by Olaparib in wild-type embryos, we performed γ-H2AX/Caspase3 and γ-H2AX/phospho (p)-Chk2 marker analysis." (PMID 33854442, 2021).
colorectal tumors (1 paper, 2022). "Based on the greatly elevated levels of pSer139 γ-H2AX in the tumor surface epithelium of ApcMin/+NHE3−/− mice, we can also speculate that loss of NHE3 in colorectal tumors leads to escalated DNA damage and local changes in surface barrier integrity." (PMID 36042372, 2022).
cyst (1 paper, 2021). A sac-like closed membranous structure that may be empty or contain fluid or amorphous material. "Consistent with previous findings, γ-H2AX was localized to cyst-lining epithelial cells and peri-cystic areas in Pkd1RC/RC mice, but this was also not different between vehicle and NaNO3 groups." (PMID 33886581, 2021).
differentiated thyroid carcinoma (1 paper, 2019). Differentiated thyroid carcinoma (DTC), also known as papillary or follicular thyroid carcinoma, is a slow-growing malignancy usually presenting in adults as an asymptomatic thyroid mass. "Recent studies by Scherthan and Lassmann measured the induction, persistence, and disappearance of radiation-induced γ-H2AX and 53BP1 foci after the first 131I therapy of patients with differentiated thyroid carcinoma." (PMID 31138230, 2019).
dilated cardiomyopathy (1 paper, 2025). Cardiomyopathy which is characterized by dilation and contractile dysfunction of the left and right ventricles. "Necroptosis, neutrophil extracellular trap formation, cardiac muscle contraction, and dilated cardiomyopathy, among others, are some pathways affected by downregulated proteins such as Pgam5, Slc25a4, and H2ax as well as Myl2, Myl3, Atp2a1, and Tpm2." (PMID 41011134, 2025).
emphysema (1 paper, 2019). "We also observed low phosphorylation of H2AX, which activates DSBs repair signaling, in emphysema." (PMID 30696938, 2019).
endometrioid adenocarcinoma (1 paper, 2020). An adenocarcinoma characterized by the presence of malignant glandular epithelial cells resembling endometrial cells. "H2AX protein was abundantly expressed in both high- and low-grade serous samples, as well as in mucinous and endometrioid adenocarcinomas." (PMID 32887437, 2020).
ependymoma (1 paper, 2014). A WHO grade II, slow growing tumor of children and young adults, usually located intraventricularly. "Recent studies have shown that short-term telomerase inhibition with MST-312 induces DNA damage as measured by gamma H2AX expression, independent of telomere shortening in primary ependymoma cells." (PMID 25307264, 2014).
epilepsy (1 paper, 2025). A brain disorder characterized by episodes of abnormally increased neuronal discharge resulting in transient episodes of sensory or motor neurological dysfunction, or psychic dysfunction.
Erythema (1 paper, 2023). Redness of the skin, caused by hyperemia of the capillaries in the lower layers of the skin. "Interestingly, when the UV spectra was isolated and used alone, it appeared to confer a trend towards greater H2AX upregulation than full spectrum irradiance for the equivalent erythema dose." (PMID 37770588, 2023).
fibrosarcoma (1 paper, 2009). A malignant mesenchymal fibroblastic neoplasm affecting the soft tissue and bone. "The phosphorylation of Chk2, Atm and H2AX shortly after ionizing radiation was normal in representative lines from wt mice (lanes 1,2,7–10) but, as expected, Chk2 phosphorylation was absent in the fibrosarcomas from Atm-null mice (lanes 3–6)." (PMID 19421407, 2009).
foot and mouth disease (1 paper, 2022). A viral infectious disease that results in infection in cattle and swine, has material basis in foot-and-mouth disease virus, which is transmitted by contaminated fomites, or transmitted by ingestion of food contaminated with infected meat or animal products. "We demonstrated that human enterovirus A71 (EVA71), a primary causative agent for hand, foot, and mouth disease (HFMD), increased the level of the DNA damage response (DDR) marker γ-H2AX." (PMID 35067196, 2022).
fungal infection (1 paper, 2012). "As DNA damage may cause chromosomal instability, we then asked whether the number of γ-H2AX foci, markers of DNA double-strand breaks, were modified by fungal infection." (PMID 22396644, 2012).
gastritis (1 paper, 2025). Inflammation of the stomach. "Similarly, we observed strong immunostaining of ACVR1 and γ-H2AX in gastritis tissues with H. pylori infection." (PMID 39924917, 2025).
HIV-1 infection (1 paper, 2008). The type species of lentivirus and the etiologic agent of acquired immunodeficiency syndrome (AIDS). "DNA damage foci containing phosphorylated ATM and H2AX were detectable in syncytia present in the brain or lymph nodes from patients with HIV-1 infection, as well as in a fraction of blood leukocytes, correlating with viral status." (PMID 18560558, 2008).
Hodgkins lymphoma (1 paper, 2013). A heterogeneous group of malignant lymphoid neoplasms of B-cell origin characterized histologically by the presence of Hodgkin and Reed-Sternberg (HRS) cells in the vast majority of cases. "The relatively lower value for the specificity and positive predictive value with the γ-H2AX expression-based approach may be a result of pharmaceutical modifiers and the lower irradiation doses applied to two of the patients (with non-hodgkin’s lymphoma) in our study." (PMID 23803252, 2013).
hypothyroidism (1 paper, 2022). Abnormally low levels of thyroid hormone. "It shows that among the patients showing a high sensitivity (for both γ-H2AX and MN induction), 80% and 82% of them achieved hypothyroidism conditions, respectively." (PMID 36077557, 2022).
Infarct (1 paper, 2024). "Inhibiting H2AX improved cardiac function, reduced myocardial infarct area, and mitigated mitochondrial damage in the MI/R group." (PMID 39257436, 2024).
laminopathy (1 paper, 2009). A rare genetic disorder caused by mutations in genes encoding proteins of the nuclear lamina. "Whydoes XPA colocalize with the laminopathy-induced DSBs marked by γ-H2AX inaging progeroid cells?" (PMID 19851476, 2009).
Lewis lung carcinoma (1 paper, 2025). "And the γ‐H2AX+ percentages of Lewis lung carcinoma (LLC) cells were greatest in the VP + IR group, which indicated that VP + IR brought about more DNA damage than VP or IR alone." (PMID 40231790, 2025).
macrocytic anaemia (1 paper, 2016). "To investigate the pathogenesis of macrocytic anaemia and increased Howell-Jolly bodies associated with the loss of H2AX, we performed comprehensive bone marrow studies comparing wild-type and H2AX knockout mice." (PMID 26791933, 2016).
mantle cell lymphoma (1 paper, 2018). Mantle cell lymphoma is a rare form of malignant non-Hodgkin lymphoma affecting B lymphocytes in the lymph nodes in a region called the ``mantle zone''. "Cotreatment of mantle cell lymphoma (MCL) cells with AF and ABT-888 (PARPi) increases synergistically the apoptosis of ATM-proficient MCL cells, with increased γ-H2AX foci induction in the DNA and depletion of p-Chk1 (a downstream target of ATR signaling)." (PMID 29770165, 2018).
multiple sclerosis (1 paper, 2016). A progressive autoimmune disorder affecting the central nervous system resulting in demyelination. "γ-H2AX expression in peripheral blood mononuclear cells (PBMCs) was recently proposed as a diagnostic and disease activity marker for multiple sclerosis (MS)." (PMID 26820970, 2016).
Myocardial fibrosis (1 paper, 2025). "Our findings confirm the involvement of the Sirt1/γ-H2AX pathway in the myocardial fibrosis observed in PF mice." (PMID 40297134, 2025).
myocardial ischemia (1 paper, 2024). A disorder of cardiac function caused by insufficient blood flow to the muscle tissue of the heart. "Inhibition of H2AX was associated with enhanced cardiac functionality, diminution of the infarct region, and mitigation of mitochondrial detriment in myocardial ischemia/reperfusion models in mice." (PMID 39257436, 2024). "In light of this, our study probes into the involvement of H2AX in the context of myocardial ischemia/reperfusion incidents." (PMID 39257436, 2024). "Initially, the study aimed to elucidate the function of phosphorylated H2AX in myocardial ischemia-reperfusion (I/R) events in murine models." (PMID 39257436, 2024). "Our findings indicate a marked upregulation of p-H2AX in the myocardial tissues of mice undergoing myocardial ischemia-reperfusion." (PMID 39257436, 2024). "H2AX's role in myocardial ischemia-reperfusion (I/R) is complex and layered." (PMID 39257436, 2024). "Collectively, these observations suggest that targeting H2AX could be a viable therapeutic strategy for mitigating myocardial ischemia/reperfusion injuries." (PMID 39257436, 2024).
neuroendocrine tumor (1 paper, 2023). "The γ-H2AX foci, induced by 177Lu-DOTATOC, have been reported as predictors of response to treatment in SSTR-expressing neuroendocrine tumor cells in both in vitro and in vivo models." (PMID 38140100, 2023).
neutropenia (1 paper, 2022). A decrease in the number of neutrophils found in the blood. "Moreover, DNA damage (responses), associated with replicative stress, were indiscernible between HSCs in neutropenia and controls, as assessed by the accumulation of Ser139-phosphorylated H2AX histone (γH2AX), which forms at the sites of DNA damage." (PMID 36496394, 2022).
non-alcoholic fatty liver disease (1 paper, 2017). "Additionally, non-tumoral liver from SH-HCCs showed a higher incidence of non-alcoholic fatty liver disease and a higher number of α-SMA-positive stellate cells expressing γ-H2AX and p21Waf1/Cif1 than that from C-HCCs (P <0.05, all)." (PMID 28273155, 2017).
pancreatic ductal adenocarcinoma (1 paper, 2024). An infiltrating adenocarcinoma that arises from the epithelial cells of the pancreas. "In this study, our objective was to elucidate the impact of γ-H2AX expression in pancreatic ductal adenocarcinoma." (PMID 38502354, 2024). "In summary, we describe high γ-H2AX expression as an independent factor for worse patient survival in a patient cohort with pancreatic ductal adenocarcinoma." (PMID 38502354, 2024). "This study, which is a part of the multi-center PANCALYZE study, investigated the role of γ-H2AX in pancreatic ductal adenocarcinoma." (PMID 38502354, 2024). "Considering our findings that highlight the significant role of γ-H2AX in patients with pancreatic ductal adenocarcinoma (PDAC), future research should explore the potential of γ-H2AX as a non-invasive biomarker in peripheral blood." (PMID 38502354, 2024).
parasite infections (1 paper, 2024). "Overall, the proportion of cells experiencing DNA damage foci (= γ-H2AX-positive BUVEC) increased with parasite infections, a finding that revealed T. gondii haplotype-dependent." (PMID 38524184, 2024).
Peri-Implantitis (1 paper, 2023). An inflammatory process with loss of supporting bone in the tissues surrounding functioning DENTAL IMPLANTS. "In peri-implantitis epithelial cells, membranous proteins expression showed differences in the levels of γ-H2AX, iNOS, NOX2, MPO and the PAD4/MPO ratio." (PMID 37232785, 2023).
periodontitis (1 paper, 2021). An acute or chronic inflammatory process that affects the tissues that surround and support the teeth. "The effect of periodontitis-associated bacteria on the expression of γ-H2AX in oral tumor-bearing mice was detected by immunohistochemistry." (PMID 34660289, 2021).
pleural tumors (1 paper, 2010). "γ-H2AX protein expression was then measured in a human NSCLC H322 orthotopic pleural tumor xenograft in mice." (PMID 20700484, 2010). "The pleural tumors from the mice treated with LacZ along with cisplatin or NPRL2 weakly stained for γ-H2AX." (PMID 20700484, 2010).
pulmonary TB (1 paper, 2023). "Another histone, H2AX, well known for its epigenetic modification by phosphorylation, acetylation, and ubiquitination in DNA damage, has demonstrated similar epigenetic events contributing to the development of active pulmonary TB." (PMID 38138142, 2023).
Rectal prolapse (1 paper, 2016). Protrusion of the rectal mucous membrane through the anus. "In contrast, the Lpd-/- mice, with rectal prolapse with EHS infection, showed significantly increased percentage of H2AX-positive cells (20/1000 enterocytes, p<0.001) compared to the control mice." (PMID 27045955, 2016).
Rotavirus infection (1 paper, 2025). Infection with any of the rotaviruses. "In this study, we aimed to determine the effects of HSP-27, Caspase-3, IL-2, γ-H2AX, HMGB-1, SP-D, and GDH on the pathogenesis of rotavirus infection by using biomarkers of lung and liver injury in neonatal diarrheic calves naturally infected with rotavirus, both in vivo and postmortem." (PMID 41515946, 2025).
secondary biliary cirrhosis (1 paper, 2020). Secondary biliary cirrhosis develops due to long-term partial or total obstruction of the large bile ducts outside of the liver. "Two of three patients who died of secondary biliary cirrhosis had BilIN lesions, and the positive expressions of γ-H2AX and S100P were detected in the BilIN lesions of one of the two patients." (PMID 33369464, 2020).
serous ovarian carcinoma (1 paper, 2024). "Based on these results we tested H2AX expression by immunohistochemistry using paired biopsies that we obtained from a high-grade serous ovarian carcinoma patient carrying a pathogenic somatic mutation in BRCA2 (c.3376 G > T/ p.Glu1126Ter)." (PMID 38789420, 2024).